CD4 (CD4 molecule)
Diseases named in the same sentence as CD4 in open-access papers (continued):
Sharing a sentence is not in itself a finding about the gene and the disease.
cervical carcinoma (continued). "For example, a study analyzed the infiltration of CD4+ and CD8+ lymphocytes in cervical cancer tissue and peripheral blood of Indian women during a period of 12 months." (PMID 34553029, 2021). "We examined the recombinant human SPAG9 (rhSPAG9) as an antigenic source for generating efficient DCs to stimulate CD4+ and CD8+ T cell responses for future DCs-based vaccine trials in cervical cancer patients." (PMID 34493268, 2021). "Using flow cytometry, Fan and colleagues investigated the prognostic impacts of PD-1 expression and density of CD4+ and CD8+ lymphocytes in 47 cervical cancer patients." (PMID 34830902, 2021). "In addition, high CD8/CD4 was associated with improved short-term survival in head and neck squamous cell carcinoma and was significantly correlated with the absence of lymph node metastases in cervical carcinomas, thus indicating a favourable prognosis." (PMID 32758195, 2020). "A notable finding of this study was that women with cervical cancer exhibited decreases in NK%, CD3%, and CD4% and an increase in CD8% after RH with PLND." (PMID 32309426, 2020). "Research on precancerous lesions and cervical cancer management of HIV-seropositive patients focusing on the quality of life of those treated; the effectiveness of the treatment method considering CD4+ count and ART is required." (PMID 32276672, 2020). "This study investigated serum interleukin-10 (IL-10) levels, changes in peripheral blood CD4+CD25+ regulatory T cell (PBCDT) ratios, and the prognosis of cervical cancer (CC) patients." (PMID 30517305, 2018). "We previously demonstrated that the frequency of CD4+ and CD8+ T cells expressing the co-inhibitory marker program death-1 (PD-1) was increased in cervical cancer patients when compared to healthy controls." (PMID 28344877, 2017). "We have synthesized 46 BVdU phosphoramidate derivatives 8–53 possessing improved cytotoxic activity against three tumour cell lines; murine leukemia (L1210), human CD4+ T-lymphocyte (CEM) and human cervical carcinoma (HeLa)." (PMID 27818111, 2016). "For instance, decreased proportions of tumor-infiltrating CD4+ T cells with reversed CD4+/CD8+ ratios were highly correlated with rapid tumor growth and lymph node metastasis in cervical carcinoma." (PMID 25605488, 2015). "Taken together, our results reveal the existence of two separate CD4+NKG2D+ T cell subsets defined by the co-expression or absence of CD28, the latter more likely to be present in patients with cervical cancer." (PMID 26486970, 2015). "Only 13 % of the control samples expressed CD4+NKG2D+ T cells above the level of 4 %, while 39 % of cervical cancer patient samples had levels of 4 % or greater of these cells." (PMID 26486970, 2015). "In cervical cancer, HPV-specific CD4+ T cells suppress cytokine (IFN-γ, IL-2) production to interfere with the anti-tumor immune response." (PMID 24465869, 2014). "In summary, our study concluded that elevations of CD4+CD25+CD127lo/-Treg, Foxp3+ Treg, CD8+ Treg and Th17 cells exsit in peripheral blood of Uygur patients with cervical cancer." (PMID 23587428, 2013). "Increased numbers and activity of HPV specific CD4+ and CD8+ T cells can be found in cervical cancer patients after vaccination with synthetic long peptides (SLP)." (PMID 21892941, 2011). "The percentage of positive tissue staining of CD4 in chronic cervicitis group, CIN group, cervical cancer group, and peri-cancer group was 100% (20/20), 80% (16/20), 45% (9/20), and 100%(20/20), respectively." (PMID 29147220, 2011). "We chose the tissues of cervical cancer, cervical intraepithelial neoplasia (CIN), chronic cervicitis and peri-cancer tissues, and then detected the expression of HLA-I, CD8 and CD4 using SP immunohistochemistry." (PMID 29147220, 2011). "The mutual exclusion of LSP1 and TIM-3 expression on CD4+ and CD8+ T cells in the cervical cancer tissues examined in this study inferred that LSP1 and TIM-3 may exhibit counteracting effects on immune cells in TME." (PMID 40038352, 2025).
cervical carcinoma (continued). "In addition, the authors collected single-cell suspension from cervical cancer tissues and normal controls, and detected the proportion of SIGLEC9+ CD4+T-cells, SIGLEC9+ CD8+T-cells and SIGLEC9+ M1 macrophages and SIGLEC9+ TAMs by flow cytometry." (PMID 41418390, 2025). "Additionally, some laboratory tests, such as CD4 counts, HBV and HCV tests, and cervical cancer screenings, faced interruptions due to a shortage of reagents." (PMID 40589828, 2025). "As frequencies of IL-17 expressing CD4+ and CD8+ T cells systemically increased after therapy in patients with vulvar or cervical cancer, interaction of CTCs and IL-17 may favor CTC survival and their contribution to metastases." (PMID 40083005, 2025). "Cluster of Differentiation-4(CD4),Cluster of Differentiation-8(CD8), and interleukin-10 (IL-10) have long been considered to be related to cervical cancer, but the exact relationship remains unclear." (PMID 41142594, 2025). "The combination of ketamine and morphine may decrease the CD4 percentage, CD4/CD8 ratio, and the levels of IFN-γ, IL-2, and IL-17 through the JAK3/STAT5 pathway in cervical cancer." (PMID 39295870, 2024). "Activated CD4+ Th cells can produce lymphocytokines that enhance the function of CTLs and natural killer cells (NK cells), activate antigen-presenting cells (APCs), and assist in the elimination of HPV-infected and cervical cancer cells." (PMID 39252044, 2024). "We evaluated Treg frequency in dual infection of HR HPV and HIV coinfection using phenotypic markers, CD4, CD25 and intracellular Foxp3, in the peripheral blood of 51 cervical cancer and 46 non-cervical cancer participants and evaluated the effect of HIV on regulatory T cell proportion." (PMID 37670247, 2023). "In pancreatic breast and cervical cancer, the engagement of PD1 with PD-L1, expressed on Bregs cells surface, induces CD4+ and CD8+ T cell suppression and exhaustion, IL-10-secreting type-1 regulatory CD4+T cells (Tr1) expansion, and reduced Th1/Th17 responses." (PMID 37568713, 2023). "Moreover, CXCL10 suppresses myeloma by recruiting effector CD8+ T, CD4+ T, and NK cells to the tumor site, and combining CXCL10 with radiotherapy enhances its therapeutic efficacy in cervical cancer." (PMID 37430270, 2023). "Thus, there is evidence that E6 and E7 HPV epitope specific CD4+ and CD8+ T-cells can be produced in vitro, using lymphocytes extracted from lymph nodes of cervical cancer patients." (PMID 36831674, 2023). "In cervical cancer, the expression of DIAPH3 was negatively correlated with the B cell group, macrophage group, dendritic cell group, and effector T cell group and positively correlated with lymphoid progenitor cells and Th2 CD4+ T cells." (PMID 36750200, 2023). "Though our study did not have data on CD4 count because it is not routinely monitored in Malawi, previous studies have demonstrated an association between low CD4 count and abnormal VIA and cervical cancer." (PMID 35077501, 2022). "Our results on Hb, CD4 cell count, and HIV RNA viral load around cervical cancer diagnosis obtained for patients diagnosed between 2016 and 2020 may not necessarily be representative of cervical cancer patients diagnosed before 2016." (PMID 36185101, 2022). "In patients with early-stage cervical carcinoma, the absence of lymphogenic metastasis was associated with increased CD8+/CD4+ ratios and CD8+/regulatory T cells." (PMID 36612258, 2022). "Both CD4+CD25+ and FoxP3+ Tregs were reported in TILs of cervical cancer." (PMID 34553029, 2021). "In multivariate analysis, HPV negativity (HR, 12.367; 95% CI, 1.30-117.05; P= 0.028), PD-1high expression status (HR, 5.91; 95% CI, 1.03-33.82; P= 0.046) and low CD8+/CD4+ TIL ratio (HR, 22.498; 95% CI, 3.66-138.39; P= 0.001) correlated with early recurrence in cervical cancer." (PMID 34150643, 2021).
cervical carcinoma (continued). "Predominant innate and adoptive cells were increasing from normalcy to cancer (B cell, total T cell, regulatory T cells [Tregs], monocytes, neutrophils, and M2‐like macrophages) together with the decrease of CD4+ T cell and CD8+ T cell through the development of cervical cancer." (PMID 33694292, 2021). "The aim of this study was to investigate whether preoperative oral carbohydrate would attenuate postoperative changes in CD4+ T cell, CD8+ T cell, and NK cell numbers in patients with cervical cancer undergoing RH and PLND after NAC." (PMID 32309426, 2020). "CD4+ and CD8+ T cells have important roles in the natural history of HPV-infected cervical cancer." (PMID 32131750, 2020). "We investigated whether preoperative oral carbohydrate affected the postoperative percentages of T cells (CD4+ and CD8+) and natural killer (NK) cells in patients with cervical cancer treated with NAC and surgery." (PMID 32309426, 2020). "In the specific case of cervical cancer, there is no consensus regarding the role of CD4 Th17 lymphocytes." (PMID 33330068, 2020). "Furthermore, cervical cancer cells instruct primary cervical fibroblasts to produce high levels of CCL20 and to attract CD4+IL17+CCR6+ cells." (PMID 32707869, 2020). "This may be due to higher CD4 count leading to greater adherence to HIV treatment and cervical cancer screening." (PMID 33112557, 2020). "For example, the long peptide containing E6 and E7 proteins of Human Papilloma virus can be presented by both HLA Class I and II pathways, and showed efficacy in eliciting both CD4 and CD8 T cell responses which reduced tumor burden in cervical cancer patients." (PMID 31722672, 2019). "Taken together, our results reveal the existence of two separate CD4+NKG2D+ T cell subsets defined by the co-expression or absence of CD28, the latter more likely to be present in anti-inflammatory environments and in patients with cervical cancer." (PMID 26486970, 2015). "If we mainly focus on cervical cancer samples, we find at least two types of patients, one with an expanded population of CD4+NKG2D+ T cells and one without." (PMID 26486970, 2015). "Interestingly, while only 13 % of the control samples expressed CD4+NKG2D+ T cells above the level of 4 %, a much higher percentage (39 %) of cervical cancer patients had levels of 4 % or greater of these cells." (PMID 26486970, 2015). "More studies will be necessary, however, in order to demonstrate the lack of Foxp3 in expanded CD4+NKG2D+ T cells from cervical cancer patients." (PMID 26486970, 2015). "It is a fact that HIV infection results in loss of CD4+ T-cells, followed by an increase of certain but not all HPV-associated anogenital malignancies; cervical cancer, however, is an exception." (PMID 23882298, 2013). "A combination of high avidity TCR transgenic HPV16 specific CD4+ and CD8+ T cells might be ideal for the treatment of patients suffering from cervical cancer and other HPV induced malignancies." (PMID 21892941, 2011). "The expression of HLA-I, CD8 and CD4 are down-regulated or deleted in CIN and cervical cancer, and they may play important roles in the development and progression of CIN and cervical cancer." (PMID 29147220, 2011). "Moreover, CT/HPV coinfection decreases the CD4 + /CD8 + T cell ratio to below 1, coinfection also induces greater T lymphocytes’ apoptosis than HPV infection, thus impairing cell-mediated immunity and accelerating the progress to cervical cancer." (PMID 38378486, 2024). "To directly compare the effect of CAR-modified T- and NK cells against cervical cancer cells, we isolated primary NK (pPB-NK) and T (pPB-T) cells from PBMCs from the same donors and evaluated CD3 and CD56 expression profiles for NK cells and CD4 and CD8 expression for T cells." (PMID 39781381, 2024).
cervical carcinoma (continued). "We also observed in cases of cervical cancer [cervical and endocervical cancer (CESC); n = 306] that there is mostly an inverse correlation of FAT1 expression with infiltration levels of CD8+ T cells, CD4+ T cells, and dendritic cells and a positive correlation with infiltration of MDSCs." (PMID 35720420, 2022). "Contrary to our hypothesis of required synergistic mechanisms between pHR/HR HPV genotypes for cervical cancer genesis, it may be that in our study population with a low median CD4 count of 236 cells/μl (IQR: 158–374), single pHR HPV genotypes are capable of inducing cervical cancer genesis." (PMID 29587796, 2018). "However, compared with the healthy control group, the percentages of CD4+ CD25+ Treg, CD4+CD25+CD127- Treg, CD4+IL17+ Th17, CD4+CD25+Foxp3+, CD4+CD25- Foxp3+, CD8+CD25+CD127-Treg and CD8+CD25+Foxp3 were significantly higher in the cervical cancer group and the CIN group." (PMID 23587428, 2013). "Although there appears to be a correlation between degree of HIV-induced immune suppression and development of cervical neoplasia, in the study presented here, HIV-infected women with cervical cancer did not have evidence of severe immune suppression (CD4 counts < 200 cells/μl)." (PMID 20716343, 2010). "In the future, by locally administering therapeutic cervical cancer vaccines to induce local immune responses, the progression of CIN can be prevented and its regression promoted.The effectiveness of such induction may be evaluated by monitoring changes in local vaginal CD4, CD8, and IL-10 levels." (PMID 41142594, 2025). "However, the specific role of CD4 + Tcm in cervical cancer is not currently clear." (PMID 36185274, 2022). "Besides, approximate half of the patients with cervical cancer could not detect HPV16-specific CD4+ T cells responses." (PMID 31001266, 2019). "This assumption was supported by the lack of reactivity of cord blood naïve CD4+ T cells to peptides corresponding to sequences of the E6 and E7 proteins of the human papilloma virus type-18, which we otherwise showed to be immunogenic in infected healthy individuals and cervical cancer patients." (PMID 22879946, 2012). "Some unconventional T cells and non-T cells, including NK, CD4+CD25+ or FoxP3+ Tregs, Th17 cells, γ-δT cells, and acrophages, have also been used in adoptive immunotherapy for cervical cancer." (PMID 37180106, 2023). "All of these data suggest that the reversed CD4/CD8 ratios are correlated with rapid tumor growth, lymph node metastasis, and finally the poor clinical outcome of patients with cervical carcinoma." (PMID 34553029, 2021). "In this study, we found that the percentages of CD4+T and CD8+T were not significantly different between the three groups of the cervical cancer group, the CIN group, and the control group." (PMID 31316301, 2019). "CD4 counts, viral load, and ART administration did not appear to strongly affect toxicity or clinical outcomes in any anal or cervical cancer studies evaluating this effect." (PMID 30105217, 2018). "The data showed that the percentage of CD4+ T cells was not significantly different among normal control group, CIN group, and cervical cancer group (P > 0.05)." (PMID 27721577, 2016). "CD158b, which is typically confined to NK cells (or some CD8+TCRαβ+ effector T cells), appeared to be mainly expressed in CD4+NKG2D+ T cells when this population was underrepresented (range 0–2 %) in both control and cervical cancer groups (data not shown)." (PMID 26486970, 2015). "Cumulative cervical cancer mortality doubled to 46.6 per 1000 HIV-positive women who were infected at age 25, were placed on HAART when their CD4 went below 200cells/mm3 and had no screening for cervical cancer." (PMID 21483701, 2011).
cervical carcinoma (continued). "In contrast, CD4+ responses were more frequent among the women with no CIN (50%; six out of 12) or with cervical cancer (60%; three out of five), than among those with low-grade (37.5%; three out of eight) and high-grade disease (25%; four out of 16)." (PMID 15986031, 2005). "CD4+ T and CD8+ T cell expression is often suppressed or even absent in CIN and cervical cancer." (PMID 40539072, 2025). "Increased expression of CD161+ on CD4+ T cells, which may represent a specific subpopulation of TH17, was seen in papillomavirus-related cervical carcinoma patients with progressive disease, but not in patients with partial response or stable disease." (PMID 35534879, 2022). "Last but not least, we analyzed the expression of Tbet in CD4+Foxp3hi regulatory T cell clone 148.31, isolated from an HPV16+ cervical cancer patient with an ongoing local type 1 immune response, and for which we have shown its suppressive capacity in several different in vitro assays." (PMID 30658697, 2019). "Within women living with HIV, more advanced immunosuppression defined by CD4 T cell counts of below 250/ul correlated with higher numbers of detected HPV types, particularly for those without lesions and those with LSIL (p<0.05), but not for those with cervical cancer (p=0.87)." (PMID 34917506, 2021). "Another example is the CD4+ T cell immunity against human papilloma virus (HPV-16): while strong E2- and E6-specific, Th1/Th2 mixed CD4+ T cell responses are frequently detected in healthy women, they are absent or strongly impaired in patients with cervical cancer." (PMID 33546283, 2021). "The bias toward CD4+ T cell reactivity against HPV-derived epitopes is not likely a result of the culture method used here, but more a reflection of what is generally found in the spontaneous T cell response to HPV in cervical cancer, as well as among TILs from patients with head and neck cancer." (PMID 27619514, 2016).